RNF8 (ring finger protein 8)
Diseases named in the same sentence as RNF8 in open-access papers (continued):
Sharing a sentence is not in itself a finding about the gene and the disease.
infection (5 papers, 2011 to 2025). The state of being infected such as from the introduction of a foreign agent such as serum, vaccine, antigenic substance or organism. "While control MCF-7 cells maintained organized cell–cell adhesion, overexpression of RNF8 in MCF-7 cells by lenti-viruses infection led to loss of cell–cell contacts; and these cells became scattering and gain a variable cell shape." (PMID 27259701, 2016). "Neutralization assays demonstrated that supplementation with 60 μg/mL mAb 5B5 in the culture medium significantly suppressed rNF8-221K infection/replication in LMH cells compared to untreated controls." (PMID 40709180, 2025). "Down-regulation of RNF8 expression is positively selected during infection and progression to disease, and further exacerbates the genomic instability of ATL." (PMID 32453758, 2020). "Initial reduction in the gene expression of WT virus was observed as a result of RNF8 ectopic expression, but this effect was recovered as the infection progressed, probably due to ICP0-induced degradation of RNF8." (PMID 31781083, 2019). "Finally, whether the nuclear and cytosolic K63-polyubiquitin chains assembled by RNF8 during infection additionally disrupt other cellular processes such as cytokinesis also awaits future investigation." (PMID 32453758, 2020). "This implies that the reason ICP0 targets RNF8 and RNF168 for degradation is to prevent recruitment of specific DNA repair factors to viral genomes, suggesting that this recruitment is detrimental to incoming virus during early stages of lytic infection." (PMID 21698222, 2011). "During infection with wild-type virus, ICP0 expression prevented 53BP1 recruitment in the presence or absence of RNF8 and RNF168." (PMID 21698222, 2011).
neurodegenerative disease (1 paper, 2022). A disorder of the central nervous system characterized by gradual and progressive loss of neural tissue and neurologic function. "As shown in Siwei’s study, RNF8 deficiency results in neurodegeneration in mice, but how RNF8 regulates these processes and exactly how RNF8 regulates neurodegenerative diseases still need to be further explored and discussed based on the identified interactome." (PMID 35831895, 2022).
RNF8 also shares sentences with these, for which no sentence is quoted: breast tumor (2 papers); esophageal cancer (2); lung squamous cell carcinoma (2); acute promyelocytic leukemia (1); adenocarcinoma (1); amyotrophic lateral sclerosis (1); bladder tumor (1); bladder urothelial carcinoma (1); Blindness (1); cervical carcinoma (1); cholangiocarcinoma (1); clear cell renal cell carcinoma (1); colon adenocarcinoma (1); diffuse large B-cell lymphoma (1); DNA repair deficiency disorders (1); dyskeratosis congenita (1); Fanconi anemia (1); keratosis (1); malignant brain tumor (1); myocardial infarction (1); neuroblastoma (1); osteosarcoma (1); ovarian carcinoma (1); Parkinson disease (1); prostate adenocarcinoma (1); rectum adenocarcinoma (1); retinitis pigmentosa (1); rhabdomyosarcoma (1); sarcoma (1); T-cell leukemia (1).
A further 6 diseases each share a sentence with RNF8 in 1 paper.